CRP (C-reactive protein)
Diseases named in the same sentence as CRP in open-access papers (continued):
Sharing a sentence is not in itself a finding about the gene and the disease.
staphylococcus aureus infection (4 papers, 2018 to 2024). An infectious process in which the bacteria Staphylococcus aureus is present. "For CoNS infection episodes BDL and CRP were positively associated (p = 0.004), and for Staphylococcus aureus infection episodes there was a positive association between BDL and I/T ratio (p = 0.049)." (PMID 29679983, 2018). "The serum level of C-reactive protein (CRP) was also elevated by Staphylococcus aureus infection and dramatically decreased following EZM0414 treatment." (PMID 38830934, 2024). "Two patients failed to respond due to methicillin-resistant Staphylococcus aureus infection, even though the level of C-reactive protein after 30 days of treatment decreased in both cases." (PMID 36064753, 2022).
substance abuse (4 papers, 2015 to 2024). The use of a drug for a reason other than which it was intended or in a manner or in quantities other than directed. "In the high-quality studies with subjects not using antidepressants, 12/16 (75%) for IL-6 and 5 of 7 studies (71%) for CRP had excluded patients with previous/current substance abuse." (PMID 26065825, 2015). "Two trials were also excluded because they were conducted on school children; along with a further two systematic reviews taking into account MBIs with adolescents, and another two trials which were performed with substance abusers and with a C-reactive protein (CRP) level >3 mg/ml." (PMID 27807420, 2016). "The most significant predictors of END were elevated levels of LDH, CRP, and homocysteine, along with higher NIHSS scores and substance abuse such as tobacco and alcohol." (PMID 39347249, 2024).
T-cell lymphoma (4 papers, 2013 to 2023). "The relationship between CRP and long-term survival in extranidal natural killer (NK)/T-cell lymphoma was also investigated, which suggested CRP was an independent predictor of clinical outcome." (PMID 37460979, 2023). "We evaluated the prognostic role of baseline serum CRP levels in patients with extranodal natural killer (NK)/T-cell lymphoma (ENKTL)." (PMID 23724031, 2013).
thoracic aortic aneurysm (4 papers, 2019 to 2023). An aneurysm formed in the wall of the proximal portion of the descending aorta proceeding from the arch of the aorta. "While levels of several inflammatory biomarkers such as C-reactive protein (CRP) and interleukin (IL)-6 are elevated in patients with thoracic aortic aneurysms, suggesting the effects of systemic inflammation on the pathophysiology." (PMID 35473483, 2022).
thymic epithelial tumors (4 papers, 2017 to 2022). "Of note, in order to establish the specificity and sensitivity of CRP as a diagnostic tool for the three different histologies in thymic epithelial tumors larger multicenter cohort studies should be performed." (PMID 34257595, 2021). "Preoperative values for white blood cell count (WBC), C-reactive protein (CRP) and lactate dehydrogenase (LDH) were analyzed in 220 thymic epithelial tumor patients operated between 1999 and 2018." (PMID 34257595, 2021). "The only previous publication investigating the prognostic impact of CRP was performed in a combined thymic epithelial tumor cohort but the effect of CRP on overall survival was not studied in the thymus carcinoma subcohort separately." (PMID 34257595, 2021). "Accordingly, we compared the white blood cell count and circulating CRP and LDH levels in the three major histological subgroups of thymic epithelial tumors and explored their prognostic potential in patients with surgically resected thymic epithelial tumors." (PMID 34257595, 2021).
tongue squamous cell carcinoma (4 papers, 2019 to 2023). A squamous cell carcinoma that arises from the tongue. "In addition, most recently, CRP is also found to promote the propagation of tongue squamous cell in the pathogenesis of tongue squamous cell carcinoma." (PMID 31391207, 2019).
Tumor Lysis Syndrome (4 papers, 2021 to 2023). a group of metabolic abnormalities that can occur as a complication during the treatment of cancer, most commonly after the treatment of lymphomas and leukemias. "Thus, as in tumor lysis syndrome, serum calcium levels were negatively correlated with plasma levels of CRP, LDH, interleukin-6, and procalcitonin, which support viral replication, development of a cytopathic effect, and subsequent cell death." (PMID 37551398, 2022). "In one patient, a tumor lysis syndrome occurred after the first dose of tebentafusp—including a decrease in prothrombin time and highly elevated LDH, C-reactive protein, uric acid and creatinine in serum." (PMID 37444540, 2023). "Interestingly, Pt #17 showed low levels of IFNG, IL6, IL1B, C-reactive protein (CRP) and Ferritin, suggesting the grade 3 CRS might be attributed to tumor lysis syndrome or other inflammation pathways." (PMID 34518515, 2021).
varicella (4 papers, 2020 to 2024). "Infectious etiologies were investigated with complete blood count, C-reactive protein (CRP), blood culture, urine culture, and analysis of cerebrospinal fluid for varicella and herpes." (PMID 39529138, 2024). "The varicella titers showed a negative correlation with the level of ALT (Rho = −0.384, p = 0.005), the level of AST (Rho = −0.405, p = 0.003), procalcitonin (Rho = −0.319, p = 0.048), the sedimentation rate (Rho = −0.404, p = 0.008) and the level of CRP (Rho = −0.378, p = 0.012)." (PMID 33614298, 2021).
ventricular tachycardia (4 papers, 2010 to 2025). A disorder characterized by an electrocardiographic finding of three or more consecutive complexes of ventricular origin with a rate greater than a certain threshold (100 or 120 beats per minute are commonly used). "However the cause of the elevation of CRP in these patients and its relation to ventricular tachycardia are unclear." (PMID 20885777, 2010). "Moreover, there is a higher level of CRP in patients soon after ventricular tachycardia, and this probably tends to decrease after the event." (PMID 20885777, 2010). "Our findings support the hypothesis that there is a higher level of CRP in ARVD/C patients soon after ventricular tachycardia and that this probably tends to decrease after the ventricular tachycardia." (PMID 20885777, 2010). "The results suggest that the CRP level may not be associated with aetiology or pathogenesis of ventricular tachycardia." (PMID 20885777, 2010).
visceral leishmaniasis (4 papers, 2011 to 2024). A severe form of leishmaniasis characterized by irregular bouts of fever, substantial weight loss, swelling of the spleen and liver, and anemia (which may be serious). "It is interesting to note that alpha-1-acidglycoprotein has been evaluated along with serum amyloid A and C-reactive protein as potential markers for predicting response to therapy in visceral leishmaniasis." (PMID 21906353, 2011).
acute acalculous cholecystitis (3 papers, 2021 to 2025). "Furthermore, the predictive values of the inflammatory markers (CRP, WBC, PCT, NLR, PLR, and SII) for gallbladder gangrene in acute acalculous cholecystitis patients were comprehensively analyzed utilizing the ROC curves." (PMID 41163918, 2025).
Acute encephalopathy (3 papers, 2018 to 2023). "AESD: acute encephalopathy with biphasic seizures and late reduced diffusion; CRP: C-reactive protein; FS: febrile seizures; PCT: procalcitonin." (PMID 31911824, 2019). "Here, we retrospectively investigated levels of serum PCT, C-reactive protein (CRP), and inflammatory cytokines (IL-6, TNF-α, and IFN-γ) in the second phase of patients with acute encephalopathy with biphasic seizures and late reduced diffusion (AESD)." (PMID 29725488, 2018).
acute-on-chronic liver failure (3 papers, 2021 to 2025). Acute-on-chronic liver failure (ACLF) is an extreme condition during the natural history of chronic HBV infection, with a relatively high short-term mortality. "Venous ammonia predicts hepatic decompensation, non-elective liver-related hospitalisation, acute-on-chronic liver failure, and liver-related death, independently of established prognostic indicators including C-reactive protein and hepatic venous pressure gradient." (PMID 36873421, 2023).
airway hyperresponsiveness (3 papers, 2012 to 2024). "Relationship between body composition and systemic inflammation (leptin, CRP), airway inflammation and airway hyperresponsiveness in males." (PMID 22296721, 2012). "Relationship between body composition and systemic inflammation (leptin, CRP), airway inflammation and airway hyperresponsiveness in females." (PMID 22296721, 2012).
alopecia areata (3 papers, 2016 to 2026). Loss of scalp and body hair involving microscopically inflammatory patchy areas. "Accordingly, the present study aimed to evaluate and compare inflammatory markers—including RDW, MPV, MLR, NLR, PLR, SII, ESR, and CRP—across patients with severe and mild alopecia areata, as well as healthy control subjects." (PMID 41517644, 2026).
Alpha-thalassemia (3 papers, 2015 to 2020). Alpha-thalassemia is an inherited hemoglobinopathy characterized by impaired synthesis of alpha-globin chains leading to a variable clinical picture depending on the number of affected alleles. "sTfR had the highest contribution (9.1%) to hemoglobin variability; followed by AGP (3.3%), alpha‐thalassemia (2.5%), child's age (2.1%), CRP (1.9%), and fever (1.9%)." (PMID 32884740, 2020). "Although the level of ALT and CRP were not significantly different between two groups, there was a positive correlation between hsCRP and ALT as well as ferritin (r = 0.3, p = 0.03 and r = 0.4, p = 0.001 respectively) only in alpha thalassemia group." (PMID 25722965, 2015).
amebiasis (3 papers, 2011 to 2023). A parasitic infectious disorder caused by amoebas. "Amebiasis cases can show elevated CRP values, and also, an interesting study found that CRP was significantly increased in the blood of children infected with Entamoeba histolytica and Giardia lamblia (>50 mg/L)." (PMID 37873776, 2023). "Other studies confirmed CRP as good parameter of inflammation and disease activity in IBD or amebiasis separately but we didn’t find data about correlation in CRP and both disease simultaneously." (PMID 27652159, 2016). "The physical and laboratory findings showed that high fever, leukocytosis and high CRP correlated with extraluminal diseases of amebiasis." (PMID 21931875, 2011). "In our study, we found CRP significantly high in patients with comorbidity of IBD and amebiasis." (PMID 27652159, 2016).
Anal fistula (3 papers, 2014 to 2024). An abnormal connection between the epithelialised surface of the anal canal and the perianal skin. "We presented the first report of a young patient with WD complicated by CD, who was admitted to the hospital because of repeated low fever, elevated C-reactive protein for 3 years, and anal fistula for 6 months." (PMID 37327274, 2023). "A 16-year-old boy was admitted to the first affiliated hospital of China Medical University because of repeated low fever, elevated C-reactive protein (CRP) for 3 years, and anal fistula for 6 months." (PMID 37327274, 2023). "In the 3 CD cases having ectopic MUC5AC expression, increases in CRP and CDAI (CDAI ≥150) were observed as signs of flare-up in 2 patients, while the remaining patient developed anal fistula, for which the Seton technique was performed surgically." (PMID 24829572, 2014). "The patient’s anal fistula gradually healed after medication, there was no fever, the patient’s CRP and erythrocyte sedimentation rate returned to normal, and his weight recovered." (PMID 37327274, 2023).
anaplasmosis (3 papers, 2019 to 2022). "While human anaplasmosis has been reported very rarely in Austria, it should be considered as a differential diagnosis in febrile patients with low leukocyte and platelet counts with elevated levels of C-reactive protein after exposure to tick bites." (PMID 32306908, 2020). "However, CRP levels may be important for distinguishing between the first phase of TBE and some other febrile illness such as human granulocytic anaplasmosis (HGA)." (PMID 35657098, 2022).
aortic valve disease (3 papers, 2006 to 2023). "Studied have reported that CRP is associated with the prognosis of CVD, such as atherosclerotic disease and aortic valve disease, suggesting an active role in the pathophysiology of CVD." (PMID 37646036, 2023).
Ataxia (3 papers, 2015 to 2025). Ataxia refers to impaired coordination of voluntary muscle movement. "However, after a rheumatological workup displayed elevated erythrocyte sedimentation rate (ESR) and C-reactive protein (CRP) levels, along with new symptoms of ataxia and headaches, a temporal artery biopsy was performed and confirmed the patient had GCA." (PMID 40726518, 2025).
atrophic gastritis (3 papers, 2021 to 2024). "The combination of sPG levels with miR-101-3p and high sensitive C-reactive protein also showed promising results for distinguishing between atrophic gastritis and GC and increasing the sensitivity of GC screening from 61% to 73%." (PMID 34425651, 2021).
attention deficit-hyperactivity disorder (3 papers, 2018 to 2024). A disorder characterized by a marked pattern of inattention and/or hyperactivity-impulsivity that is inconsistent with developmental level and clearly interferes with functioning in at least two settings (e.g. at home and at school). "CRP is related to increased physical activity, even in the attention deficit and hyperactivity disorder pathogenesis, mediated through changes in cytokines and neurotransmitters." (PMID 34912245, 2021).
auto-inflammatory syndrome (3 papers, 2020 to 2023). "Two patients had bouts of low-grade fever and increased serum levels of CRP and amyloid A, as found in auto-inflammatory syndromes." (PMID 34829952, 2021). "S100A8/A9 was superior to C-reactive protein (CRP) for differentiating systemic JIA from other autoinflammatory syndromes and systemic undifferentiated recurring fever syndrome." (PMID 33224145, 2020). "However, it has been suggested that CRP is more useful in differential diagnosis, where a high CRP level that does not decrease during treatment could be an indicator of auto-inflammatory syndrome." (PMID 37511088, 2023).
biliary tract cancer (3 papers, 2017 to 2023). "Given these trends, if foods such as seaweed, kelp, garlic, and onions can reduce CRP and other inflammatory marker levels, as shown in previous studies, they may also help reduce the risk of biliary tract cancers." (PMID 28288186, 2017). "Previously, general inflammatory markers in plasma (CRP, albumin) were validated as independent negative prognostic factors for overall survival for patients with resectable biliary tract cancer (BTC)." (PMID 37404757, 2023). "Several studies have reported that preoperative indicators, such as serum albumin and CRP levels, as well as widely recognized tumor markers (CEA and CA 19-9) may also serve as prognostic indicators of biliary tract cancer outcomes; however, the NLR and LMR scored over these factors in this study." (PMID 32321522, 2020).
bleeding (3 papers, 2020 to 2023). "CRP and MIF levels were detected significantly higher in hemophilia patients with acute joint bleeding than patients without acute joint bleeding." (PMID 33023246, 2020).
Brugada syndrome (3 papers, 2011 to 2024). A genetically heterogeneous condition characterized by complete or incomplete right bundle branch block accompanied by ST elevation in leads V1-V3. "Inflammation caused by CRP has been linked to many cardiac disorders, one of which is Brugada Syndrome (BrS)." (PMID 37754956, 2023).
bursitis (3 papers, 2017 to 2023). Inflammation or irritation of a synovial bursa, the fibrous sac that acts as a cushion between moving structures of bones, muscles, tendons or skin. "Longer duration of IV therapy was associated with methicillin-resistant Staphylococcus aureus (MRSA), older age, vascular disease, diagnosis of bursitis, treatment with teicoplanin in one cohort and male sex, high baseline CRP and prolonged duration of symptoms prior to OPAT in another cohort." (PMID 28683717, 2017). "In our study, the presence of bursitis was demonstrated by USG, MRI, or PET-CT in all patients who had normal ESR and CRP values at the time of their diagnosis." (PMID 37773830, 2023). "After the presence of bursitis was demonstrated with ultrasonography in patients with normal ESR and CRP rates, they were accepted to have PMR." (PMID 37773830, 2023). "While bursitis can be demonstrated with ultrasonography in patients who are clinically evaluated to have PMR, APRs such as SAA other than ESR and CRP can also be used." (PMID 37773830, 2023). "Patients undergoing diagnostic shift had a higher frequency of GH synovitis, shoulder PD, higher CRP, WBC, PLT and Hb and longer time to achieve remission, while those maintaining diagnosis had bilateral exudative LHBT and SA-SD bursitis, higher ESR, lower Hb and shorter time to remission." (PMID 37498353, 2023).
calcinosis (3 papers, 2020 to 2022). Deposition of calcium in the tissues. "Bearing in mind that especially TFR is usually associated with early and more severe SSc, calcinosis cutis with severe SSc, focusing on these manifestations and its connection to CRP levels might be a valid target for a consecutive study." (PMID 36743676, 2022).
central serous chorioretinopathy (3 papers, 2023 to 2025). "This study aimed to investigate the risk factors associated with central serous chorioretinopathy (CSC) and analyze the relationship between vascular endothelial growth factor (VEGF), high-sensitivity C-reactive protein (hs-CRP), erythrocyte sedimentation rate (ESR), and CSC." (PMID 39347542, 2024).
cerebral atherosclerosis (3 papers, 2022 to 2023). Atherosclerosis of the cerebral vasculature. "CRP could induce direct neuronal damage through pro-inflammatory responses, and act as a cardiovascular risk factor leading to the development of cerebral atherosclerosis." (PMID 38071240, 2023). "Inflammation, as assessed by hs-CRP, was demonstrated to reduce the cognitive function through an acute phase affecting tissue damage by stimulating the deposition of amyloid β or developing cerebral atherosclerosis that can harm the brain function." (PMID 35252292, 2022).
Cerebral atrophy (3 papers, 2021 to 2025). Atrophy (wasting, decrease in size of cells or tissue) affecting the cerebrum. "Global reductions in brain volume and decreased cortical thickness in the insula and prefrontal cortex have been linked to increased blood CRP levels, and increased CRP has also been associated with cerebral atrophy in diverse neurodegenerative disorders." (PMID 38593073, 2024).
cervicitis (3 papers, 2011 to 2022). An acute or chronic inflammatory process that affects the cervix. "Kangfuxiaomi shuan II could significantly reduce the levels of CP, CRP, and MDA in serum of rats with cervicitis, and significantly increase the activity of SOD in serum of rats with cervicitis (P<0.01)." (PMID 34852132, 2021).
Chlamydia infection (3 papers, 2017 to 2023). "Chlamydia infection in acute PID is associated with increased level of inflammatory markers, such as CA-125, ESR and CRP, incidence of TOA, operation risk, and longer hospitalization." (PMID 28086838, 2017). "The CA-125 level was the strongest predictor of chlamydia infection, followed by the ESR and CRP level." (PMID 28086838, 2017). "CRP levels were significantly increased among the patient groups as compared with controls, regardless of a previous Chlamydia infection." (PMID 30804931, 2019). "The strongest predictor of chlamydia infection was CA-125, followed by ESR and CRP." (PMID 28086838, 2017).